IL6 (interleukin 6)
Diseases named in the same sentence as IL6 in open-access papers (continued):
Sharing a sentence is not in itself a finding about the gene and the disease.
tumor (continued). "In tumor, however, CAFs secrete pro-tumorigenic growth factors like fibroblast growth factor (FGF), TGF-β, VEGF, and IL-6, that lead to ECM remodeling, enhance angiogenesis, supporting tumor cell proliferation, invasion, and immune evasion." (PMID 40438111, 2025). "The interaction between macrophages and tumor cells triggers the release of proinflammatory cytokines such as tumor necrosis factor (TNF), interleukin-1 (IL-1), and interleukin-6 (IL-6), which contribute to endothelial damage and cell detachment." (PMID 40034639, 2025). "Similarified GNAS upregulation by LPS stimulation enhances IL-6 expression by elevating m6A methylation of mRNA, while GNAS knockdown diminishes IL-6, thereby inhibiting tumor growth." (PMID 40034695, 2025). "Inflammatory cytokines, including VEGF, IL-1, IL-6, and TNF-a, are produced by tumor cells that promote cellular growth and differentiation, but concurrently cause endothelial cell dysfunction leading to greater capillary hyperpermeability." (PMID 40103850, 2025). "In the breast cancer tumor-bearing animals, PVSO reduced tumor growth, and suppressed serum and hypothalamic inflammatory cytokines (TNF-α, IL-1β, and IL-6) and NF-κB signaling." (PMID 40993108, 2025). "The continuous release of inflammatory factors (such as IL-6 and TNF-α) and dysregulated immune systems can directly damage lymphocyte DNA, leading to the inactivation of tumour suppressor genes." (PMID 41567225, 2025). "The secretion of the cytokine IL-6 can also activate the STAT3 signaling pathway, thereby influencing the entire process of tumor initiation and progression." (PMID 40487290, 2025). "MDSCs are recruited to the TME through various tumor-derived growth factors such as GM-CSF, G-CSF, VEGF, macrophage colony-stimulating factor (M-CSF), and IL-6." (PMID 40109854, 2025). "Immune cells infiltrating the tumor microenvironment (TME) release numerous pro-inflammatory cytokines, including interleukin-6 (IL-6), which amplify local inflammation." (PMID 41007818, 2025). "In vivo, they effectively reduced tumor size in MDA-MB-231 xenograft models, accompanied by increased cytokine levels (IL-2, IL-6, TNF-α, IFN-γ) and many CD3+ cells." (PMID 40281554, 2025). "Key signaling pathways, such as TGF-β, IL-6/STAT3, and NF-ҝβ, drive a microenvironment that facilitates tumor growth, angiogenesis, and metastasis." (PMID 41614820, 2025). "SC-derived cytokines such as IL-6, TNF-α, and TGF-β play pivotal roles in promoting tumor cell proliferation, invasion, and perineural invasion (PNI) through activation of critical signaling pathways like STAT-3 and NF-κB." (PMID 40567365, 2025). "The IL6-induced JAK/STAT3 signaling pathway elevates the expression of MMP9 in OC cells, degrading the extracellular matrix (ECM) and creating pathways for tumor invasion and metastasis." (PMID 40427188, 2025). "Memory B cells in an inflamed tumor microenvironment may actively participate in anti-tumor immunity and can function as potent antigen-presenting cells that restimulate T cells and secrete pro-inflammatory cytokines (e.g., TNFα, IL-6, IFN-γ) to recruit and activate other immune effectors." (PMID 41222706, 2025). "For instance, Cytokines such as IL-6 and TGF-β, secreted by Tumor Cells, have been shown to inhibit the activity of immune cells, thereby facilitating Immune Evasion." (PMID 41333481, 2025). "BFT also influences immune cells by activating the TLRs signaling pathway, which upregulates IL-6 and TNF-α, further leading to the activation of STAT3 and NF-κB, thereby inhibiting anti-tumor immunity and promoting tumorigenesis." (PMID 40297806, 2025). "SRGs are predominantly expressed in epithelial tumor cells, driving key oncogenic pathways such as epithelial-mesenchymal transition (EMT), KRAS signaling, and IL6-JAK-STAT3 activation, highlighting their contribution to tumor progression and invasiveness." (PMID 40821814, 2025).
tumor (continued). "This target-selective phagocytic activity was associated with increased secretion of pro-inflammatory cytokines (IL-6, IL-1β, TNF-α, IL-12) following co-culture with tumor cells." (PMID 41388305, 2025). "PLX51107 treatment also resulted in a significant reduction of IL-6 in the plasma of EMT6 (95% reduction, P < 0.01) and 4T1 (78% reduction, P < 0.05) tumor–bearing mice." (PMID 40762981, 2025). "TAMs, particularly those polarized toward the M2 phenotype, secrete immunosuppressive cytokines such as IL-6, IL-10, and TGF-β, which suppress anti-tumor immunity and promote cancer cell proliferation, survival, and metastasis." (PMID 40282189, 2025). "Interestingly, PTIS-related vulnerabilities in PTR tumor growth were found to extend to metastasis with post-mortem analysis at experiment endpoint showing enhanced inhibition of tumor skin/abdominal wall invasion in PTR tumor variants after IFNAR1KD and IL6 inhibition compared to P controls." (PMID 39663510, 2025). "SASP components such as IL-6, IL-8, and vascular endothelial growth factor (VEGF) enhance tumor cell proliferation, angiogenesis, and metastasis." (PMID 40356750, 2025). "Inhibits tumor growth, induces tumor cell apoptosis, increases M1-type macrophages in tumor tissue, elevates TNF-α and IL-6, and reduces IL-10." (PMID 40766304, 2025). "“Cold” tumors are often dominated by immunosuppressive cytokines, such as IL6, IL10, and TGFβ, which suppress the recruitment and activation of immune cells, creating an environment that promotes tumor progression." (PMID 40427188, 2025). "Circulating cytokines, including IL-6, IL-8, and tumor necrosis factor-alpha (TNF-α), correlate with systemic inflammation, tumor burden, and immunotherapy resistance." (PMID 40881677, 2025). "SASP includes a variety of cytokines (e.g., IL-6, IL-8), chemokines (CXCL1, CCL2), growth factors (VEGF, TGF-β), and proteases, such as MMPs, that collectively modify the TME, promote tumor invasion, and support metastatic spread." (PMID 41373662, 2025). "Advanced assays quantify circulating cytokines and chemokines, such as IL-6, TNF-α, and CXCL12, which reflect the immune microenvironment and tumor progression." (PMID 40881677, 2025). "In summary, our results showed no indication for Fusobacterium-mediated M2 polarization of macrophages in the CRC tumor samples but, in contrast, a pro-inflammatory TME driven by inflammatory cytokines such as CXCL8, IL-6, and TNF-α." (PMID 40895532, 2025). "Galiellalactone also suppresses the production of immunosuppressive cytokines IL-10, IL-1β, IL-6 in monocytes, while reducing factors that drive MDSC recruitment and expansion in tumor cells such as IL-8 and GM-CSF." (PMID 41228234, 2025). "MSCs promote tumor progression primarily by secreting pro-inflammatory cytokines and growth factors such as VEGF, IL-6, TNF-α, and SDF-1." (PMID 40784879, 2025). "Multiple studies have demonstrated that IL-6 induces VEGF expression via the JAK/STAT3 signaling pathway, thereby contributing to angiogenesis and tumor invasion." (PMID 41010841, 2025). "A similar mechanism occurs in CRC, where tumor-derived EVs enriched with miR-21-5p interact with TLR7 on Kupffer cells in the liver, driving macrophage polarization and IL-6 secretion." (PMID 40574836, 2025). "Aging immune cells also promote tumor metabolic reprogramming via cytokines and secreted factors: Senescent immune or stromal cells secrete pro-inflammatory SASP factors (e.g., IL-6, IL-8, TNF-α, CXCL1), activating STAT3 and NF-κB pathways in tumor cells." (PMID 40881346, 2025). "The downregulation of miR-126 significantly inhibited tumor growth in HBs and reduced the proportion of CD44+ CD90+ CD133+ cells, increasing the expression of IL-6, Oct4, SRY, TGF-β, and β-catenin in mouse tumor tissues." (PMID 41393242, 2025). "We propose a mechanistic model in which chronic cytokine signaling—particularly via IL-6, TGF-β, and TNF-α—drives a feedforward loop that reinforces tumor aggressiveness." (PMID 40933989, 2025).
tumor (continued). "IL6 further upregulates immune checkpoint molecules such as PD1 and CTLA4 on CTLs, promoting tumor immune evasion." (PMID 40427188, 2025). "This multipronged modulation resolves chronic inflammation by lowering IL-6/IL-8-driven neutrophil infiltration and macrophage M2 polarization, thereby converting the TME from a tumor-permissive state to one that restricts malignant progression." (PMID 40703657, 2025). "By inhibiting IL6, it is possible to reduce the phosphorylation of STAT3, thereby decreasing the proliferation and anti-apoptotic capabilities of tumor." (PMID 40535567, 2025). "NF-κB signaling is triggered in macrophages by tumor-derived cytokines such as TNF-α and IL-1β, further enhancing the production of IL-6 and IL-10, that further promote tissue remodeling and angiogenesis." (PMID 40160820, 2025). "Cytokines like IL-6 and TNF-α, as well as tumor-infiltrating lymphocytes (TILs), also serve as key indicators of immune activation." (PMID 40092992, 2025). "As tumors progress, however, SASP components exhibit pro-tumorigenic functions: growth factors stimulate tumor cell proliferation; TGF-β and IL-6 induce epithelial-mesenchymal transition to enhance invasion." (PMID 40703657, 2025). "Mechanistically, C1q+ TAMs interact with cancer stem cells via C1q–C1q receptor signaling, modulate cytokine secretion (e.g., IL-6, MCP-1) to either promote tumor progression or, through the AMPK/JAK/STAT pathway, enhance anti-tumor immunity." (PMID 41200171, 2025). "Sustained pro-inflammatory cytokine production (notably IL-6, TNF-α, and IL-2R) induces CD4+ T-cell exhaustion and accelerates tumor progression." (PMID 40969752, 2025). "In AOM/DSS-induced CRC mice, KGM-CUR/PSM microspheres significantly improved survival and inhibited CRC tumor growth, and effectively reduced the expression of inflammatory cytokines (TNF-α, IL-1β, IL-6) and myeloperoxidase (MPO)." (PMID 40733148, 2025). "Existing literature suggests that IDO1 promotes EMT in BC through the IL-6/STAT3/PD-L1 signaling pathway, enhancing the migratory and invasive potential of tumor cells." (PMID 40287406, 2025). "IL-6, in turn, downregulates tumour-suppressive miR-34a and promotes EMT, tumour growth, and dissemination." (PMID 40361472, 2025). "Tumor cells induce inflammation by activating white blood cells and releasing inflammatory cytokines (e.g., TNF-α, IL-1β, IL-6, IL-21, and TGF-β), which are critical at the tumor site." (PMID 41153842, 2025). "Persistent hepatic inflammation in Child–Pugh B patients can also activate pathways like IL-6/STAT3 and IL-17, promoting tumor cell proliferation, invasion, and drug resistance." (PMID 40481877, 2025). "Conversely, the NF-κB pathway upregulates pro-inflammatory cytokines (interleukin-6 (IL-6), VEGF, (IL-8)), Inducible nitric oxide synthase (iNOs), TGF-β, indirectly boosts WNT/β-catenin, thus fueling inflammation and tumor growth." (PMID 40732979, 2025). "It induces chronic inflammation via cytokines such as IL-1β, IL-6, and TNF-α, fostering tumor progression." (PMID 39941737, 2025). "Studies have shown that mice treated with IL-6-NIS-MSCs and subsequent 131I therapy experienced significant tumor growth delay and increased survival rates." (PMID 39911388, 2025). "In response, a range of prognostic and predictive biomarkers—ranging from tumor markers such as SCC-Ag and CA125, to molecular markers including HPV subtypes, to immune markers like IL-6—has been investigated to enhance treatment outcomes." (PMID 41244922, 2025). "Regulatory NK cells secrete IL‐6, which activates STAT3 signaling in MDSCs, thereby suppressing T cell responses and promoting tumor immune escape." (PMID 41357670, 2025). "For example, TAMs secrete cytokines such as IL-6 and TNF-α, which upregulate glycolytic enzymes like HK2 and LDHA in tumor cells, amplifying lactate production and fostering a pro-tumorigenic environment." (PMID 41007256, 2025).
tumor (continued). "Numerous studies have reported significant associations between the expression levels of inflammatory cytokines—including IL-6, CXCL9, TNF-α, IL-17A, and IL-32—and LUAD tumor stage, metastasis, and prognosis." (PMID 40136462, 2025). "At the same time, the cytokines, such as IL-6, IL-8, CXCL12, and CXCL8, secreted by CAFs, have also been proven to be important factors in suppressing the anti-tumor immune response of pancreatic cancer." (PMID 41156387, 2025). "Pro-inflammatory cytokines such as interleukin-6 (IL-6) and tumor necrosis factor-alpha (TNF-α) activate signaling pathways like STAT3 and NF-κB, driving tumor proliferation and survival." (PMID 40486628, 2025). "Compared with other treatments, combination therapy with ICAM‐1–Dxd and B7‐H3‐CD3 significantly elevated the concentrations of tumor‐suppressive cytokines, including TNF‐α, IL‐6, and IFN‐γ, to a greater extent." (PMID 39996528, 2025). "M2d macrophages are activated by TLR antagonists, IL-6, and adenosine, with adenosine promoting the expression of IL-10 and VEGF, thereby exacerbating angiogenesis and tumor progression." (PMID 40375990, 2025). "For example, IL-6, frequently overexpressed by CAFs, synergizes with VEGF to support tumor angiogenesis and adaptive resistance to VEGF-targeted therapies." (PMID 40534854, 2025). "In summary, our study highlights that IL-6, VEGF, PDGF-BB, IP-10, MCP-1, and IL-9 exhibit complex and often context-dependent roles in tumours, making them both potential biomarkers and therapeutic targets." (PMID 40733274, 2025). "Meanwhile, IL-6 activates the Ras-ERK and PI3K-Akt signaling pathways to further accelerate tumor growth." (PMID 40563367, 2025). "Since STAT3 activation is sustained by IL-6 signaling, CCNB1 likely contributes to a positive feedback loop between IL-6 and JAK-STAT3, further reinforcing tumor immune evasion." (PMID 40430484, 2025). "This study aimed to explore the relationship between the presence of F. nucleatum and the expression of inflammation-related genes (IL6, IL1B, IL10, IL17, TNF) in tumor and matched normal tissue of Kazakhstani CRC patients." (PMID 41267807, 2025). "CAF subtypes can secrete soluble factors, such as interleukin-6 (IL-6), TNF-α, and granulocyte-colony stimulating factor (G-SCF), that modulate the immune response, leading to either anti-tumor or pro-tumor effects." (PMID 39979981, 2025). "The IL6/IL6R/gp130 complex activates signaling pathways via STAT3 and MAPK activation, which not only drive angiogenesis but also contribute to tumor progression." (PMID 40427188, 2025). "In this study, we provide evidence that tumor-induced systemic inflammation activates NF-κB signaling in the hypothalamus, leading to upregulation of key pro-inflammatory genes (IL-1β, TNF-α and IL-6) within the CNS." (PMID 40993108, 2025). "Cytokines, such as CCL-2, IL-6, IL-8, IL-10, IL-13, and TNF-α, exhibit tumor-specific secretion profiles." (PMID 40777043, 2025). "To substantiate these findings, we employed a subcutaneous tumor model using a mouse ESCC cell line (mEC25) and treated the mice with anti-PD-1 monotherapy, anti-IL-6 monotherapy, or a combination of both." (PMID 41309527, 2025). "The polarized M2 macrophages can increase phosphoglycerate kinase 1 (PGK1) phosphorylation in tumor cells, mediated by 3-adenosine phosphate-dependent protein kinase 1 (PDPK1) in tumor cells by secreting IL-6." (PMID 40297580, 2025). "Within the tumor microenvironment (TME), stromal cells and malignant clones secrete IL-6, which activates gp130/JAK/STAT3 cascades through IL-6 receptor (IL-6R) binding." (PMID 40733153, 2025). "In vivo studies showed that treatment with BB-NVs increased the proportion of CD3+CD4+ and CD3+CD8+ cells in tumor tissue and spleen and significantly increased the expression of anti-tumor cytokines TNF-α, IL-6, IL-10, and IFN-γ." (PMID 40284501, 2025).
tumor (continued). "In vivo efficacy was evaluated in AOM/DSS-induced CRC mice, monitoring tumor growth, inflammatory markers (TNF-α, IL-1β, IL-6, MPO), and gut microbiota composition." (PMID 40733148, 2025). "Pro-inflammatory M1 macrophages release inflammatory mediators such as IL-6, TNF-α, and iNOS, inciting robust pro-inflammatory immune responses that inhibit tumor cell proliferation." (PMID 40670983, 2025). "Tumor samples from hu-BLT mice treated with sNK cells and AJ2 feeding showed increased IFN-γ secretion and reduced IL-6 secretion." (PMID 40940758, 2025). "Inflammation can inhibit T-cell function and alter the microenvironment to generate pro-tumor cytokines like IL-6 and TNF-α, thereby diminishing the anti-tumor efficacy of ICIs." (PMID 41001020, 2025). "This phase is characterized by pro-inflammatory cytokines, including tumor TNF-α, IFN-γ, IL-1, and IL-6." (PMID 40446079, 2025). "The proangiogenic cytokines identified in our study, including IL-6, IL-8, PDGF, and VEGF, play a key role in inducing angiogenesis and promoting tumor progression." (PMID 40143164, 2025). "IL-6 plays a central role in AML progression by directly stimulating leukemogenic processes, reshaping the inflammatory tumor microenvironment, and orchestrating immunosuppressive mechanisms." (PMID 40557150, 2025). "Biological evidence highlights the involvement of pro-inflammatory cytokines (IL-6, IL-1β, TNF-α), NF-κB signaling, and activation of the tryptophan–kynurenine pathway (IDO), suggesting a link between tumor-related processes and mood alterations." (PMID 41514529, 2025). "CSCs, in turn, produce IL-6, creating a positive feedback loop that sustains CSC populations within the tumor microenvironment." (PMID 39896297, 2025). "The secretion of IgG by plasma cells can activate Fc gamma receptors (FcγR) on macrophages, leading to production of IL-6, IL-10, and CCL20 while suppressing the anti-tumor immune response." (PMID 40453088, 2025). "Tumor cells exhibit decreased expression of OPN when treated with anti-IL-6 antibodies, indicating that IL-6 serves as an upstream regulator of OPN expression." (PMID 40664639, 2025). "The exposure to IL-6 leads to the chronic induction of STAT3 phosphorylation, which promotes further growth and invasion of these tumor cells." (PMID 40940764, 2025). "The traditional herbal formula Shashen-Maidong Decoction suppresses tumor growth under intermittent hypoxia by restoring mitochondrial SOD2 expression and downregulating IL-6/JAK2/STAT3 signaling, thereby linking oxidative and inflammatory responses." (PMID 40722961, 2025). "The S1, S5, and S6 treatment groups showed enhanced anti-tumor immunity, with reduced TGF-β, IL-6, and IL-10 levels." (PMID 40507880, 2025). "Although we found some mild CD8+ T cell dependence of IL-6, IL-10, VEGF, and IL-1α in the tumor bed of LLCova-bearing mice, the biggest difference was evident in the proinflammatory cytokines IFN-γ and TNF-α." (PMID 40553564, 2025). "Tumour and WAT Il6 mRNA levels remained unchanged, while cancer induced skeletal muscle (SkM) Il6 (2‐fold, p = 0.0016 vs. Ctrls) at both temperatures." (PMID 40237521, 2025). "These microbes promote the secretion of pro-inflammatory cytokines (such as IL-6, TGF-β, and TNF-α) by CAFs, which enhances tumor cell proliferation and drives tumor growth and metastasis." (PMID 41473772, 2025). "Among these, IL-1β, IL2, IL6 play critical roles in activating immune cells and amplifying proinflammation responses, while TNFα and IL27 can directly inhibit the growth of tumor cells." (PMID 40046011, 2025). "Tumor TGF−β is associated with shorter EFS; it may be produced under MSC-NB cell-monocyte interaction, inducing an amplifying loop, where TGF-β stimulates the production of IL-6 and sIL-6Rα, protecting TAMs from spontaneous death and, in turn, promoting further TGF-β production." (PMID 40092980, 2025).